TLR4 (toll like receptor 4)
Diseases named in the same sentence as TLR4 in open-access papers (continued):
Sharing a sentence is not in itself a finding about the gene and the disease.
metabolic syndrome (continued). "In line with the present study, we reported recently that LPS‐enriched cEVs from metabolic syndrome patients contribute to the low‐grade inflammation in these patients and trigger endothelial dysfunction by activation of TLR4." (PMID 36708245, 2023). "Free fatty acids released from hypertrophic adipocytes and from fetuin-A, which functions as a carrier protein, are similarly involved in TLR4 activation in metabolic syndrome." (PMID 35712350, 2022). "TLR4-KO mice showed reduced metabolic syndrome symptoms, e.g., abnormal glucose metabolism, suggesting that TLR4 activation by various exogenous and endogenous ligands is an important contributor to the pathogenic processes." (PMID 35712350, 2022). "TLR4 is a known target of miRNA-146a and plays a key role in lipid uptake; the increase of miRNA-146a protein caused by the rs2910164 polymorphism inhibits the expression of TLR4, thus reducing lipid uptake and resulting in dyslipidemia." (PMID 34646311, 2021). "It was demonstrated in an experimental study that atherogenic dyslipidemia enhances autoimmune responses in a Toll-like receptor 4 and IL-27-dependent manner." (PMID 34439776, 2021). "Along with increased TLR4 expression, enhanced NF-κB activation, inflammatory activity and aggravated dyslipidemia were observed in the IH treated group." (PMID 29673358, 2018). "After TLR4 interference, the instability of plaques was decreased with attenuated inflammation and dyslipidemia." (PMID 29673358, 2018). "The most prominent finding of this investigation is that BB protect against chronic kidney disease in the Zucker rat model of metabolic syndrome by attenuating TLR4 expression and reducing oxidative stress in the kidney." (PMID 25372283, 2014). "Accumulation of PA may lead to dyslipidemia and inflammation through Toll-like receptor 4 (TLR4), G-protein coupled receptors (GPRs), and the NF-κB signaling pathway." (PMID 41008536, 2025). "A study of TLR4’s role in glycolipid metabolism could contribute to the prevention of metabolic syndrome, which seriously affects human health." (PMID 38275739, 2024). "Targeting hepatocyte TLR4 could have therapeutic potential in the prevention and treatment of metabolic syndrome induced by alcohol overconsumption." (PMID 36979389, 2023). "Thus, it is interesting to investigate the involvement of histone modifications in SFA-induced TLR4 activation in metabolic syndrome." (PMID 35490239, 2022). "Furthermore, SCFAs also help in alleviating metabolic syndrome in a high-fat-diet mouse model by inhibiting the expression of pro-inflammatory cytokines, such as IL-1β and IL-6 as well as toll like receptor 4 (TLR4) in adipose tissue." (PMID 36176581, 2022). "High-mobility group box one protein (HMGB1), which functions primarily as a nuclear protein, is released from chromosomes of dead cells and from hypertrophied adipocytes in metabolic syndrome patients, and functions secondarily as an endogenous ligand for TLR4." (PMID 35712350, 2022). "Moreover, dyslipidemia contributes to an increase in several endogenous ligands for TLR4 including hyaluronic acid, biglycan and oxidized LDL." (PMID 30530865, 2019). "TLR4 signaling may also play an important role in IH-mediated AS plaque progression by aggravating dyslipidemia." (PMID 29673358, 2018). "It has been shown that the TLR4 gene may have a major influence on adiposity, and metabolic syndrome in addition to its well known role in the immune response." (PMID 19772581, 2009). "Therefore, TLR4 signaling in different cell types may trigger opposite effects on the development of the metabolic syndrome." (PMID 36979389, 2023). "Similarly, toll like receptor 4 (TLR4) mutation or oral antibiotics protected against high fructose diet-induced NAFLD in mice, highlighting the importance of the gut-liver axis in the pathogenesis of dietary fructose associated NAFLD and metabolic syndrome." (PMID 30469339, 2018).
metabolic syndrome (continued). "It will be important to investigate whether or not TLR4 Asp299Gly linked to another genetic modifier of the metabolic syndrome." (PMID 19772581, 2009). "We obtained overlapping genes between Danshen compounds and dyslipidemia, and through a PPI network analysis, key target genes such as JAK2, STAT3, PI3K, AKT1, and TLR4 were acquired." (PMID 39598338, 2024). "Myricetin significantly reduced LPS-induced metabolic endotoxemia and systemic inflammation, corrected dyslipidemia and restored liver function in NAFLD rats by regulating the TLR4/NF-κB signaling pathway." (PMID 36937840, 2023). "Especially, the activation of NFκB, mediated by toll-like receptor 4 (TLR4), is involved not only in an acute inflammatory response, but also in the chronic, low-grade inflammation that can induce metabolic syndrome." (PMID 31083375, 2019). "Toll-like receptor 4 (TLR4), the key pattern-recognition receptor of LPS, plays a crucial role in innate immune system and links to metabolic syndrome." (PMID 27051672, 2016). "Therefore, the attenuation of oxidative stress and ROS to suppress CD36-mediated TLR4/6-IRAK4/1 signaling and NLRP3 inflammasome activation by cinnamaldehyde and allopurinol may be a promising therapeutic strategy for the treatment of metabolic syndrome-associated heart disease." (PMID 27270216, 2016). "In conclusion, dyslipidemia induces osteoclast differentiation on the alveolar bone surface by activation of TLR2 and TLR4 in the rat apolipoprotein E knockout model." (PMID 23295061, 2013). "Gene expression of TLR2, TLR4 and RANKL was 1.90, 1.37, and 1.52 times higher in periodontal tissues obtained from the dyslipidemia group than in those obtained from the control group, respectively (p < 0.05)." (PMID 23295061, 2013). "In human studies, subjects with metabolic syndrome receiving blueberry showed a significant decline in superoxide and total ROS together with a reduction of inflammatory markers and reduced gene expression of TNF-α, TLR4, and IL-6." (PMID 35898615, 2022). "TLR4 has been known to be involved in the development of NAFLD and metabolic syndrome (29, –, 32)." (PMID 32019793, 2020). "The results demonstrated that age, dyslipidemia, atrial fibrillation, triglyceride, MR (grades 2 to 4), mean TLR2+/CD14+ cells, TLR2+/CD14+ cells <25%, TLR4+/CD14+ cells <0.25%, mean MPO+/CD14+cells, MPO+CD14+ cells <20%, sST2 <14,000 (pg/mL), and mean sST2 were significantly predictive of mild CCS." (PMID 32054047, 2020). "It is worth noting that the lipopolysaccharide (LPS) receptor TLR4 which binds Gram-negative bacteria LPS, was found to promote diet-induced metabolic syndrome." (PMID 29997595, 2018). "It has thus been demonstrated that a high-fat diet increases the proportion of an LPS-containing micro biota in the gut, and that mice that do not express TLR4 or CD14 receptors are protected from this induced metabolic syndrome compared to normal mice." (PMID 20148136, 2010). "Apigenin could attenuate dyslipidemia and subsequent atherosclerotic conditions through down-regulating SREBP-1c, SREBP-2, FAS, stearyl-CoA desaturase 1, HMG-CoA reductase, TLR-4, Npc1l1, MyD88, p-IκB-α, and NF-κB p65 which are involved in inflammation and atherosclerotic plaques formation." (PMID 38629096, 2024). "We confirmed the upregulation expression of TLR4 in MS by immunostaining TLR4 in the brain cortex of the WT-HFD group as compared to the WT-ND group, and it was possible to correlate this increased expression with the observed metabolic syndrome-related changes." (PMID 35488354, 2022). "Toll-like receptor 4 (TLR4) contributes to the development of NAFLD (nonalcoholic fatty liver disease) and MetS (metabolic syndrome)." (PMID 26930651, 2016).
acute kidney injury (100 papers, 2008 to 2026). Sudden and sustained deterioration of the kidney function characterized by decreased glomerular filtration rate, increased serum creatinine or oliguria. "Klotho has also been shown to cause the degradation of TLR4, the receptor for LPS, via a deglycosylation-associated proteolytic process and thus attenuate LPS-induced acute kidney injury." (PMID 33478014, 2021). "A study involving TLR4-deficient mice administered a toxic dose of cisplatin (20 mg/kg) to induce acute renal failure within 72 h and reported significantly reduced markers of inflammation, nephrotoxicity, and renal function and decreased renal injury and histological abnormalities." (PMID 33805488, 2021). "Among the 11 human TLRs, TLR4 has been implicated in the pathogenesis of acute and chronic renal disorders such as acute kidney injury (AKI), renal fibrosis, and DKD." (PMID 29861832, 2018). "The most significant contribution of this study lies in the development of a novel TLR4 inhibitor, which was used to rescue acute kidney injury in the AKI model." (PMID 41516327, 2025). "In the study of the pathogenesis of acute kidney injury, PAMPs and DAMPs can bind to TLR4, and the expression of TLR4 increases with kidney injury and/or infection." (PMID 40356926, 2025). "While HO‐1 protects cells from oxidative damage, TLR4 activation exacerbates inflammatory pathways, worsening renal failure." (PMID 41019175, 2025). "Importantly, investigations have documented a profound association between TLR4/NF-κB activation and the occurrence of acute kidney injury, with the activation of this pathway likely paving the way for SA-AKI symptoms." (PMID 39839617, 2024). "Increasing evidence indicates that TLR4 plays an indispensable role in the pathogenesis of acute kidney injury." (PMID 37175958, 2023). "Oleic acid is able to bind to the TLR4–MD-2 complex, inhibit the TLR4-signaling cascades, and ameliorate LPS-induced acute kidney injury." (PMID 38068746, 2023). "Longanetin, isolated from Cornus fruits, is a novel TLR4 inhibitor to protect mice from rhabdomyolysis-induced acute kidney injury." (PMID 36552516, 2022). "It was reported that TAK-242 alleviated crush injury-induced acute kidney injury via inhibiting the TLR4/NF-κB signaling pathways in rats." (PMID 35845572, 2022). "As for the impacts of valsartan and tripterygium glycosides on TLR4 expression, a related study has reported that valsartan prevents glycerol-stimulated acute kidney injury via reducing the TLR4 and NF-kappaB expression." (PMID 36061150, 2022). "TLR4 is even involved in regulating the processes of the infiltration of leukocytes in the kidney during ischemic acute kidney injury and the release of IL-6." (PMID 34638569, 2021). "Renoprotective effect of paricalcitol via a modulation of the TLR4-NF-κB pathway in ischemia/reperfusion-induced acute kidney injury." (PMID 32508821, 2020). "SAA binds to Toll-like receptor 4 (TLR4) to prevent the potential effects of LPS-challenged acute kidney injury." (PMID 32581777, 2020). "Extracellular histones can interact with TLR2, TLR4 and TLR9 to cause organ damages in acute kidney injury and sterile inflammatory liver injury." (PMID 32432055, 2020). "It has been well studied that the activation pathway of TLR4 in response to LPS infection contributes to acute kidney injury." (PMID 30915370, 2019). "This study aimed to evaluate the protective effect of hydroxysafflor yellow A (HSYA) on ischemia/reperfusion (I/R)-induced acute kidney injury via the TLR4/NF-κB pathway, both in vitro and in vivo." (PMID 29907783, 2018). "Recently, it was demonstrated that paeonol protected endotoxin-induced acute kidney injury via the inhibition of toll-like receptor 4 (TLR4) and nuclear factor kappa B (NF-κB) signal pathway." (PMID 30186353, 2018).
acute kidney injury (continued). "In summary, our results demonstrated that IL-18Rα-mediated signaling plays critical roles in CD4+ T-cells and APCs and was markedly faster at responding to IFN-γ and IL-18 than TLR4 stimulation in the pathogenesis of LPS-induced acute kidney injury." (PMID 29261164, 2017). "All these explanations lead us to the conjecture that LPS play a major role in renal failure however, further studies using TLR4 knockout mice will be required to determine the exact role of LPS in renal dysfunction." (PMID 26580567, 2015). "According to a recent report, paricalcitol protected against ischemia/reperfusion-induced acute kidney injury by suppressing TLR4-NF-κB mediated inflammation." (PMID 26691774, 2015). "Recent work has clearly demonstrated the induction of inflammatory responses by extracellular histones from dying cells via TLR2 and TLR4 in acute kidney injury." (PMID 24454474, 2013). "Several studies document a similar role for TLR2, TLR4, and MyD88 in postischemic acute renal failure of C57BL/6 mice." (PMID 21544241, 2011). "However, TLR4 activation enhances inflammatory pathways and exacerbates renal failure, whereas HO‐1 aids cells in defending against oxidative damage." (PMID 41019175, 2025). "Myeloid differentiation factor 88 (MyD88), a central adaptor in the TLR4 pathway and a known contributor to acute kidney injury, showed increased protein expression in kidneys from septic rats, as determined through Western blotting and confirmed through immunohistochemistry/immunofluorescence." (PMID 40869248, 2025). "In addition to periodontal pathogens, endogenous DAMPs and uremic toxins that build up in renal failure also trigger TLR4 activation." (PMID 41002387, 2025). "Furthermore, dioscin-loaded zein nanoparticles were demonstrated to alleviate LPS-induced acute kidney injury by modulating the MIRLET7I-TLR4 (toll like receptor 4) signaling pathway." (PMID 40851276, 2025). "Hederasaponin C, a natural product, effectively inhibits lipopolysaccharide (LPS)-induced acute kidney injury in mice by specifically targeting Toll-like receptor 4 (TLR4) and modulating the phosphatidylinositol 4,5-bisphosphate (PIP2)/NF-κB/NLRP3 signaling pathway." (PMID 38740765, 2024). "Toll-like receptor 4 (TLR4) is a well-characterized pattern recognition receptor, and increasing evidence has shown that TLR4 mediated inflammatory response, plays a pivotal role in the pathogenesis of acute kidney injury." (PMID 36674930, 2023). "Additionally, hispidulin attenuates LPS-induced acute kidney injury in mice by reducing the expression of pro-inflammatory cytokines and Toll-like receptor 4 (TLR4)." (PMID 37764491, 2023). "Additionally, the TLR4-NF-κB signaling pathway has been shown to alleviate inflammation in acute kidney injury." (PMID 38049739, 2023). "Although it has been suggested that IPC ameliorates acute kidney injury induced by limb ischemia/reperfusion via inhibiting Toll-like receptor 4 (TLR4) and nuclear factor kappa B (NF-κB) signaling in rats, more specific mechanisms require further exploration in this regard." (PMID 35224648, 2022). "Myeloid cells and TLR4 play a critical role in acute kidney injury." (PMID 34568976, 2021). "Acute kidney injury (AKI) after transplantation of human deceased donor kidneys is associated with upregulation of tubular toll like receptor 4 (TLR4), but whether TLR4 is required for AKI is unknown." (PMID 34376755, 2021). "In the kidney, TLR4-/- mice were shown to be resistant to endotoxin-induced acute renal failure, a phenomenon associated with a lack of a systemic TNF-α response." (PMID 30399158, 2018). "Thus, HSYA can protect renal function from I/R injury by ameliorating acute kidney injury and partly by promoting tubular cell survival via the TLR4/NF-κB pathway." (PMID 29907783, 2018). "Previous studies showed that TLR4 played an important role in LPS-induced acute kidney injury." (PMID 27813491, 2016).
acute kidney injury (continued). "TLR4 plays an important role in LPS-induced acute kidney injury." (PMID 27813491, 2016). "Moreover, TLR-2 and TLR-4 plays an imperative role in the pathophysiology of acute kidney injury and may be a potential therapeutic target to lessen renal damage in response to various pathological stimuli." (PMID 37045926, 2023). "This review summarizes the present data regarding the role of TLR4 and its endogenous ligand activation in the course and development of acute kidney injury (AKI)." (PMID 36674930, 2023). "Moreover, miR-374a-3p may regulate acute kidney injury by targeting TLR4/NF-κB pathway to reduce the rate of apoptosis and the generation of inflammatory cytokines." (PMID 35909518, 2022). "It was also possible that MIF may mediate acute kidney injury via CD74/TLR4-NF-κB signaling." (PMID 32964038, 2020). "However, further study incorporating the use of gene knock-out mice for TLR4, MyD88 and/or NF-κB should be performed in order to confirm the role of TLR4/MyD88/NF-κB pathway activation in dexmedetomidine mediated attenuation of acute kidney injury after orthotopic autologous liver transplantation." (PMID 26585410, 2015). "TLR4-mediated inflammation resulting in glomerular endothelial swelling may be an important part of the pathogenesis underlying Gram-negative septic acute kidney injury." (PMID 25182709, 2014). "TNF and TLR4 are involved in regulating immune responses during kidney injury, whereas IGFBP7 serves as a marker for acute kidney injury." (PMID 41567268, 2026). "Interestingly, tubule-specific deletion of TLR-4, an LPS-binding receptor, retained the efficacy of intravenous fluid treatment in LPS-induced acute kidney injury (AKI)." (PMID 34069405, 2021). "Acute kidney injury (AKI), a common complication of Gram-negative bacterial sepsis, is caused by Toll-like receptor 4 (TLR4) activation." (PMID 30915370, 2019). "In addition, in CD38 KO mice, there is increased TLR4 expression compared to WT mice, which favors the overexpression of IFN-γ and acute kidney injury." (PMID 41488275, 2025). "Additionally, a study performed using C3H/HeOuJ mice showed that lipopolysaccharides (LPS) stimulated the activation of TLR4, thereby triggering the release of tumor necrosis factor-α (TNF-α), which, consequently, induced renal failure." (PMID 38287815, 2024). "Toll-4 receptors (TLR4) and NLPR3 inflammasome are pattern-recognition receptors responsible for activating inflammatory responses and are assigned to play a significant role with gasdermin (GSDMD) in acute kidney injuries." (PMID 36986437, 2023). "Following acute kidney injury, pulmonary TLR4 and TLR2 up-regulated significantly in non-treatment (BIR and BNX) groups compared with the sham group but decreased in the treatment (BIR+BMSCs and BNX+BMSCs) groups in comparison." (PMID 35911649, 2022). "Some studies have found that vinorelbine protects against cisplatin-induced acute kidney injury (AKI) by activating Nrf2/HO-1 signaling pathway and hindering TLR4-IFN-γ-CD44 cell inflammatory cascade when investigating the molecular mechanism of renal protection against nephrotoxicity." (PMID 35186957, 2021). "In conclusion, TLR2 and TLR4 expressions are elevated in nephrotic diabetic patients with renal failure or without renal failure compared to normal individuals." (PMID 33442388, 2020). "TLR2 and TLR4 expressions are much more elevated in nephrotic diabetic patients with renal failure compared to nephrotic diabetic patients without renal failure." (PMID 33442388, 2020). "AKI (acute kidney injury); RUNX1 (runt-related transcription factor 1); SNHG5 (small nuclear RNA host gene 5); TLR4/NF-ĸb (toll-like receptor 4/nuclear factor-ĸB); I/R (ischemia/reperfusion); DR6 (death receptor 6)." (PMID 40217756, 2025).